IL6 (interleukin 6)
Diseases named in the same sentence as IL6 in open-access papers (continued):
Sharing a sentence is not in itself a finding about the gene and the disease.
myeloma (continued). "Observational studies have shown higher LDH, ALP, CRP, and IL-6 levels with extensive liver involvement in patients with multiple myeloma." (PMID 26221143, 2015). "High levels of Baculoviral inhibitor of apoptosis repeat-containing 5 (BIRC5/Survivin) expression in multiple myeloma cells correlates with reduced Bim transcription in response to IL-6 deprivation and shorter overall survival of patients." (PMID 26405162, 2015). "Siltuximab, a monoclonal antibody against IL-6, is in clinical trials for therapies including; combinatorial treatment of metastatic renal cell carcinoma, multiple myeloma, and prostate cancer." (PMID 26268945, 2015). "Here, we show that IL-6-induced STAT3 tyrosine phosphorylation is significantly enhanced in CD45+ myeloma cells in comparison with CD45- myeloma cells." (PMID 25781885, 2015). "Marizomib did not affect the viability of BMSCs, rather blocked the production of IL-6 that is triggered by myeloma cells and BMSC interaction." (PMID 26579531, 2015). "In myeloma cells, IL-6 triggers cell proliferation via at least two intracellular signaling pathways, including JAK/STAT3, and the ras-dependent mitogen-activated protein kinase (MAPK)/extracellular signal-regulated kinase (ERK) cascade." (PMID 25781885, 2015). "XIAP is highly expressed in myeloma cells and is induced by IL-6 and IGF-1-mediated activation of NF-κB/MAPK/PI3K pathways." (PMID 26009993, 2015). "IL-6, also called B-cell stimulatory factor-2 and interferon beta-2, is involved in different biological functions, including B lymph cell differentiation and myeloma and plasmacytoma growth." (PMID 26528857, 2015). "Stromal cells including monocytes and macrophages can produce inflammatory cytokines such as IL6, which promote growth and increase survival of myeloma cells 2,3." (PMID 26029369, 2015). "Inflammatory parameters such as C-reactive protein (CRP) and interleukin-6 (IL-6) at diagnosis have been also reported as prognostic in patients with multiple myeloma." (PMID 24963470, 2014). "In myeloma, IL-1 was found to stimulate IL-6 release from marrow stromal cells, which stimulates the survival and proliferation of plasma cells." (PMID 25905009, 2014). "This idea is consistent with the findings that human myeloma cells and under certain conditions even normal plasma cells can produce autocrine growths factors, such as IL-6 and APRIL." (PMID 25272036, 2014). "Various cytokines, especially IL-6 and sIL-6R, directly affect the biologic behaviors of multiple myeloma cells, and the response to IL-6 in myeloma cells is very important." (PMID 25343143, 2014). "The same study also showed that eosinophils support the growth of multiple myeloma cells in vitro via secretion of soluble factors and suggested an IL-6 independent mechanism of supporting of myeloma cell growth." (PMID 25272036, 2014). "IL-6 is a growth factor for B-lymphocytes, and crucial to the growth, proliferation and survival of myeloma cells." (PMID 25905009, 2014). "Because IL-6 is known to act in an autocrine manner, the induction of IL-6 and sIL-6R needs to be analyzed in each myeloma cell line." (PMID 25343143, 2014). "B-T2 was originally shown to downregulate IL-6 induced signaling and proliferation of a human myeloma cell line." (PMID 24612692, 2014). "To elucidate the role of CCN1 in the crosstalk between stromal cells and myeloma cells, we performed co-culture experiments with primary mesenchymal stem cells (MSC) and the interleukin-6 (IL-6)-dependent myeloma cell line INA-6." (PMID 24965524, 2014). "Based on these, we treated myeloma cells with IL-6 and sIL-6R together to determine the activation of IL-6 mediated signaling pathway." (PMID 25343143, 2014). "Based on the well-known fact that in myeloma, IL-6 is produced in an autocrine and paracrine fashion and promotes the survival and progression of tumor cells; we had expected that the induction of Th17 would have been favored in this malignancy." (PMID 25099367, 2014).
myeloma (continued). "Our results suggest that berberine suppresses multiple myeloma cell growth, at least in part, by down-regulating miR-21 levels possibly through IL6/STAT3." (PMID 25000828, 2014). "Siltuximab (CNTO 328), a monoclonal antibody against IL-6, has shown promising results for non-small cell lung cancer, ovarian cancer, prostate cancer, and multiple myeloma, among others." (PMID 24901008, 2014). "In general, multiple myeloma cells, if removed from the bone marrow, often cannot survive without feeder cells or supplementation of factors to cell cultures, e.g. IL-6 in case of the INA-6 cell line." (PMID 24965524, 2014). "Incubation of multiple myeloma cells with 5 nM IL-6, 25 nM sIL-6R, and combined treatment of IL-6 and sIL-6R (5 nM and 25 nM) for 30 min, respectively, was performed." (PMID 25343143, 2014). "Preliminary data from Phase I-II studies of anti-IL-6 in patients with multiple myeloma, castration-resistant prostate cancer and other solid tumors indicate the possible development of anti-IL-6 in cancer patients." (PMID 24886605, 2014). "We used cytokine interleukin-6 (IL-6) and soluble IL-6 receptor (sIL-6R), which is well known to regulate the biologic behaviors of myeloma cells in the progression of multiple myeloma." (PMID 25343143, 2014). "Consistently, IL-6 treatment significantly enhanced the growth of myeloma cells after 48-hour treatment with IL-6 in U266 cell line and 8226-cell line, in comparison with the treatment without IL-6 (p < 0.05)." (PMID 25422792, 2014). "Other nodules in the network correspond to cytokines with known function in myeloma pathophysiology and/or in osteolytic lesions (IL6, IL1β, CCL2, IL8 and CCL20)." (PMID 25268740, 2014). "To elucidate the role of CCN1 in the crosstalk between stromal cells and myeloma tumor cells, we performed co-culture experiments with primary MSC and the interleukin-6 (IL-6)-dependent myeloma cell line INA-6." (PMID 24965524, 2014). "The findings in this study indicated that RNA silence of STAT3, PI3K, or MAPK gene using shRNA interference robustly inhibited MCL-1 expression in IL-6 treated human MM cells, leading to remarkable myeloma cell apoptosis." (PMID 25422792, 2014). "Addition of MTM results in decreased IL-6 production and myeloma cell growth, whereas the ERK inhibitor U0126 strongly inhibits SP1 recruitment at the IL-6 promoter site." (PMID 23667526, 2013). "Myeloma cell lines are protected from apoptosis by IL-6, due to the induction of specific antiapoptotic genes." (PMID 24489445, 2013). "Previous reports showed that not only multiple myeloma cells but also BMSCs adherent to multiple myeloma cells also release IL-6 via NF-κB pathway to support MM cell growth." (PMID 24151609, 2013). "Among the three compounds that inhibit NF-κB pathway, our data showed that only TPCK suppressed IL-6 secretion remarkably from multiple myeloma cells as well as BMSCs." (PMID 24151609, 2013). "Cytokines actively produced by myeloma cells such as IL-6, IL-10, transforming growth factor-β (TGF-β), and vascular endothelial growth factor (VEGF), abundant in the BM as well as in the serum, play a role in preventing the development of functional DCs." (PMID 23818912, 2013). "TNFα and IL-6, as pivotal factors for myeloma, can be ideal targets for therapeutic purpose, either directly or by inhibiting interaction with BMSCs." (PMID 24151609, 2013). "We also analyzed the patterns of correlation between TNFα and IL-6 and the mechanisms of TNFα-induced IL-6 secretion from multiple myeloma cells." (PMID 24151609, 2013). "Interleukin-6 (IL-6) is the main growth factor for multiple myeloma (MM) and studies of epileptic patients showed elevated levels of IL-6 after carbamazepine therapy." (PMID 24385839, 2013). "TNFα potently stimulates IL-6 secretion by stromal cells and osteoblasts, and accumulated IL-6 stimulates growth of multiple myeloma cells." (PMID 24151609, 2013).
myeloma (continued). "In multiple myeloma cells, induction of autocrine interleukin-6/-18 production accounts for enhanced proliferation upon TLR activation." (PMID 24371445, 2013). "Numerous studies revealed that TNFα induces IL-6 secretion from multiple myeloma cells and bone marrow stromal cells through NF-κB pathway." (PMID 24151609, 2013). "IL-10 has been involved in the activation of myeloma cells, supporting their long term growth responding to IL-6." (PMID 23936794, 2013). "Cells were first cultured in a medium mixture of 40% DMEM + 40% IMDM, supplemented with rich fetal bovine serum and IL-6, an important cytokine that support myeloma cell growth in the bone marrow microenvironment." (PMID 24330858, 2013). "Interleukin-6 and -8, both highly secreted by endometrial CAFs, promote the growth of various tumor types including colon, multiple myeloma and non-small cell lung cancers." (PMID 23922669, 2013). "IL-6 and TNFα were significantly increased in the bone marrow aspirate samples of patients with active multiple myeloma (MM) compared to those of normal controls." (PMID 24151609, 2013). "The adhesion of myeloma cells to the stromal cells prompts the bone marrow stromal cells to secrete osteoclast-activating factors (OAFs) such as IL-1β, IL-6, and TNF-β, which further induce stromal cells and osteoblasts to secrete RANKL." (PMID 24252328, 2013). "IL-6 is known to regulate MM cell proliferation and inhibition of both myeloma plasma cell apoptosis and OC differentiation." (PMID 23818912, 2013). "After 1-h pretreatment with 1 μM RAP, myeloma LC-stimulated production of cytokines IL-6 and 8 was significantly inhibited by co-incubation with RAP." (PMID 23894629, 2013). "We found that the levels of TNFα and IL-6 were elevated in bone marrow aspirates of multiple myeloma patients." (PMID 24151609, 2013). "IL-6 acts as a paracrine growth factor for multiple myeloma, non-Hodgkin’s lymphoma, bladder cancer, colorectal cancer, and renal cell carcinoma (RCC)." (PMID 23905066, 2012). "Although increased secretion of IL-6, a cytokine critical for myeloma survival, by the pathological Gaucher’s disease macrophages might play an important role, the complete pathogenetic basis of increased risk of myeloma in Gaucher’s disease remains to be elucidated." (PMID 22936926, 2012). "In the particular case of multiple myeloma (MM), a plasma cell cancer, the adhesion between MM cells and bone marrow fibroblasts leads to the secretion of IL-6 by the latter." (PMID 22949815, 2012). "Several types of cytokines were identified in myeloma microenvironment including inflammatory molecules with a key role of IL-6 as well as angiogenic factors like VEGF and TGF-β." (PMID 22223085, 2012). "It has been demonstrated that endocytosis of light chains of Abs, excessively produced in multiple myeloma by human proximal tubule cells, leads to production of cytokines, such as IL-6, through activation of NF-kB." (PMID 22952831, 2012). "In contrast, IL-10 (immune suppressive cytokine) and IL-6 (enhancer of myeloma cell) expression was increased in MM patients." (PMID 23152910, 2012). "In multiple myeloma patients IL-6 is often synthesized by the tumor itself and by bone marrow stem cells within an autocrine growth loop." (PMID 22114899, 2011). "In fact, one of the reasons corticosteroids are effective agents against myeloma is likely because they inhibit IL-6." (PMID 24213115, 2011). "Some cancer cells, such as myeloma, begin to secrete high amounts of IL-6 to serve as an autocrine growth factor that promotes their own survival." (PMID 24213115, 2011). "Multiple members of the Src family of tyrosine kinases were coprecipitated with gp130 in lysates from multiple myeloma cells and stimulation with IL-6 led to increased activity of these Src family kinases." (PMID 21481226, 2011). "In conclusion, our data suggest that via suppressing miRNA-15a and -16 expressions, IL-6 secreted by BMSCs promotes drug-resistance in myeloma cells." (PMID 21936961, 2011).
myeloma (continued). "It should be noted that almost one third of multiple myeloma patients had IL–6 pos.–174 GG genotype and 62% IL–10 GCC haplotype." (PMID 22567049, 2011). "Normally, IL-6 induces B-cell differentiation, but in myeloma it induces proliferation and inhibits apoptosis." (PMID 22177381, 2011). "These drugs induce apoptosis of myeloma cells, interrupt the interaction between myeloma cells and stromal cells in the BM, inhibit angiogenesis and inhibit the secretion of IL–1β and IL–6." (PMID 22567049, 2011). "Among target cells, the growth of normal and myeloma plasma cells is supported by IL–6, which also induces the differentiation of myeloma plasmablastic cells into mature plasma cells." (PMID 22567049, 2011). "The myeloma cell adheres to the bone marrow (BM) microenvironment, and thereby stimulates angiogenesis and enhances the stimulation of cytokines such as IL–1β, IL–6 and IL–10." (PMID 22567049, 2011). "Overexpression of PPARγ in myeloma cells and BMSCs inhibited both basal and myeloma cell adhesion-induced IL-6 production by BMSCs." (PMID 20204067, 2010). "Genes upregulated in multiple myeloma cells exposed to the pro-proliferative cytokine IL-6 versus those that were IL-6-starved." (PMID 20500821, 2010). "BMSCs stimulate MAPK signaling in myeloma cells through IL-6R-independent mechanisms thereby circumventing the need for Stat3-mediated signaling in response to IL-6 for myeloma cell survival." (PMID 20204067, 2010). "Consistent with our data, TRAIL induced apoptosis is inhibited by IL8 in ovarian cancer cells, by IL-1β in keratinocytes, and by IL6 in multiple myeloma cells." (PMID 20661477, 2010). "Taken together, the results of these studies demonstrate that PPARγ agonists can be used to inhibit IL-6-dependent crosstalk between myeloma cells and BMSCs, validating novel therapeutic strategies that target the tumor-stromal microenvironment." (PMID 20204067, 2010). "PPARγ and its ligands effectively blocked IL-6 transcription and secretion from BMSCs that is induced in response to myeloma cell adhesion." (PMID 20204067, 2010). "IL-6 has an important role in the acute phase response and can be found in several illnesses, such as multiple myeloma and bowel inflammation." (PMID 20184737, 2010). "This drug has been reported to affect myeloma cell growth by NF-κB blockade, down regulation of cytokines such as IL-6." (PMID 19400935, 2009). "HGF potentiated IL-6-induced growth in human myeloma cell lines and in purified primary myeloma cells." (PMID 19187270, 2009). "HGF was the only growth factor among 70 highly expressed genes in malignant plasma cells compared to normal bone marrow plasma cells, and HGF and IL-6 were also shown to characterize one of four clusters of hyperdiploid myeloma." (PMID 19187270, 2009). "The results indicate that besides from being a myeloma growth factor alone, HGF can also potentiate the effects of IL-6 in myeloma proliferation and migration." (PMID 19187270, 2009). "A strong correlation between IL-6 secretion, measured by ELISA, and resistance to doxorubicin as ionizing radiations was observed in the multiple myeloma U266 and the Burkitt's lymphoma Daudi and Namalwa cells." (PMID 19956602, 2009). "We stimulated the IL-6-dependent myeloma cell lines ANBL-6, IH-1, INA-6 and OH-2 with cytokines known to promote growth of myeloma cells." (PMID 19191868, 2009). "Lenalidomide downregulates the production of IL-6 directly and also by inhibiting multiple myeloma (MM) cells and bone marrow stromal cells (BMSC) interaction, which augments the apoptosis of myeloma cells." (PMID 19674465, 2009). "Myeloma cell lines and primary samples were tested for the combined effects of IL-6 and HGF in inducing DNA synthesis and migration." (PMID 19187270, 2009). "IL-6, a major activator of Stat3, particularly in myeloma cells, is known to be under the transcriptional regulation of Stat3 itself, thereby constituting a feedback loop." (PMID 19440292, 2009).
myeloma (continued). "Inhibiting c-Met had substantial effects on IL-6-induced proliferation in four out of nine primary samples, although the frequency of this mechanism in primary myeloma patients is hard to estimate due to the low numbers of samples." (PMID 19187270, 2009). "Cultures of avicin treated myeloma cells showed a decrease in the levels of IL-6, a major inducer of Stat3 activity, which is also known to be under the transcriptional regulation of Stat3." (PMID 19440292, 2009). "The release of and response to IL-6 by myeloma cells, melanoma cells, and carcinoma cells of the head and neck, the breast and the kidney have been reported." (PMID 19497133, 2009). "The proliferation and survival of myeloma cells are also potentiated by IL-6 and IL-6 receptor signal transduction through autocrine and paracrine stimulation." (PMID 18577263, 2008). "IL-6 mediated signaling pathway is known to be involved in myeloma pathogenesis, and is one of the mechanisms of drug resistance of myeloma cells." (PMID 18577263, 2008). "IL-6 and IL-6 receptor- mediated signaling pathway is critical for the survival and proliferation of myeloma cells." (PMID 18577263, 2008). "Production of interleukin 6 in cases of renal carcinoma, for instance, has been reported to be a factor in the pathogenesis of multiple myeloma." (PMID 18853039, 2008). "Elevated levels of Interleukin-6 have been observed in conditions of rapid skeletal turnover and hypercalcemia as in Paget's disease and multiple myeloma." (PMID 17374166, 2007). "Pamidronate and other bisphosphonates inhibit the production by osteoblasts of the inflammatory cytokine interleukin-6, a growth factor essential to myeloma cells." (PMID 17374166, 2007). "Interleukin-6 (IL-6) affects the survival and proliferation of myeloma cells via autocrine and/or paracrine mechanisms." (PMID 16892169, 2006). "Interleukin-6 is produced by MM cells and promotes myeloma cell proliferation in an autocrine manner through phosphorylation of the signalling protein STAT3." (PMID 15970928, 2005). "In multiple myeloma cells IL-6 inhibits apoptosis induced by serum starvation, dexamethasone, and Fas." (PMID 16001973, 2005). "In addition, persistent IL-6/STAT3 signaling can aberrantly reactivate BCL6 expression in IL-6–dependent myeloma cells, fostering uncontrolled proliferation and treatment resistance." (PMID 41357603, 2025). "Thus, in addition to osteogenic differentiation and disrupting stromal support for MM, BMP2 and BMP6 exert direct anti-myeloma effects and inhibit IL6-mediated proliferation." (PMID 41463400, 2025). "Others have reported that IL6 promoted the interaction of the TNIK/β-catenin/TCF4 complex (multiple myeloma cells:); transcriptional activity of the β-catenin/TCF4 complex is promoted by TNIK and inhibited by SF1, which induces an alternative splicing activity." (PMID 40003000, 2025). "One of the primary growth factors driving myeloma development is IL-6." (PMID 40392374, 2025). "Given the key role of IL6 in supporting MM survival and proliferation, and our observation that BMP2 and BMP6 reduced IL6 expression in MSCs, we next assessed whether they could directly counteract IL6-induced myeloma growth." (PMID 41463400, 2025). "Overproduction of interleukin‐6 (IL‐6) is thought to be crucial for the survival of myeloma cells." (PMID 39866922, 2025). "The particularly poor OS seen among those with moderate–severe thrombocytopenia developing thrombocytosis or vice versa may reflect clonal expansion of myeloma cells expressing IL‐6, which mediates platelet production." (PMID 41278511, 2025). "Even in multiple myeloma, where IL-6 is recognized as a critical growth factor driving tumor cell proliferation and survival, the clinical efficacy of anti-IL-6 mAbs has been disappointing—despite anecdotal reports of transient benefits in select patient subgroups." (PMID 40563367, 2025). "Notch signaling in multiple myeloma also controls the release of IL-6." (PMID 38672455, 2024).